WWP1 (WW domain containing E3 ubiquitin protein ligase 1)
Diseases named in the same sentence as WWP1 in open-access papers (continued):
Sharing a sentence is not in itself a finding about the gene and the disease.
Obesity (6 papers, 2020 to 2025). Accumulation of substantial excess body fat. "In this review, we present the latest findings on WWP1 as a potential drug target and its relevance in obesity-associated disorders and metabolic tissues, particularly WAT and the liver." (PMID 41009733, 2025). "In recent years, the novel role of WWP1 as an obesity-associated molecule relevant to metabolic diseases has been reported." (PMID 41009733, 2025). "We anticipate that inhibition of WWP1 is a promising approach for a new treatment of obesity and type-2 diabetes using Adrb3 agonists." (PMID 40362456, 2025). "On the basis of our previous finding that an HFD increased WWP1 expression, we propose that WWP1 is one of the candidates that negatively regulates lipolysis owing to decreased Adrb3 expression in WAT during obesity." (PMID 40362456, 2025). "In this review, we discuss the regulation and molecular function of WWP1 and its contribution to obesity-related metabolic disorders, particularly in white adipose tissue and the liver." (PMID 41009733, 2025). "We found that HFD-induced obesity increased WWP1 protein expression in WAT, similar to our previous report." (PMID 40362456, 2025). "Recently, we found that the level of WWP1 is increased in white adipose tissue in a mouse model of obesity and that obese Wwp1 knockout (KO) mice exhibit improved whole‐body glucose metabolism." (PMID 37032433, 2023). "In summary, WWP1 participates in obesity‐related metabolic dysfunction and pathologies related to hepatic steatosis via suppressed insulin signaling." (PMID 37032433, 2023). "Further investigation of the role of WWP1 in WAT should provide insight into obesity‐related pathology in WAT." (PMID 31965758, 2020). "To evaluate the involvement of WWP1 in metabolic regulation, we previously generated and studied systemic Wwp1 knockout (KO) mice and found that Wwp1 KO mice had improved insulin sensitivity and glucose tolerance from obesity-related insulin resistance." (PMID 40362456, 2025). "We speculate that WWP1, which is increased in obesity, is a candidate for reducing catecholamine-stimulated lipolysis due to obesity." (PMID 40362456, 2025). "Obesity upregulates WW domain-containing E3 ubiquitin protein ligase 1 (WWP1) in WAT." (PMID 37928271, 2023). "Thus, WWP1 is an obesity-inducible E3 ligase that can protect against obesity-related stress in WAT." (PMID 38129384, 2023). "Wwp1 KO mice showed normal total GSH content when fed the HFD, indicating that WWP1 may contribute to the acute antioxidative response in WAT during the early stages of obesity." (PMID 31965758, 2020). "Therefore, targeting WWP1 may be useful in the treatment of obesity and type-2 diabetes through its dual functions." (PMID 40362456, 2025). "As circulating levels of palmitate and other saturated free fatty acids are increased in obesity and stimulate oxidative stress in obese adipose tissue, WWP1 may ameliorate cellular stress in obese WAT by suppressing lipotoxicity-induced ROS production and the associated Golgi stress." (PMID 41009733, 2025). "Therefore, the inhibition of WWP1 expression combined with the administration of β3-AR agonists may become a novel treatment for catecholamine resistance in obesity and diabetes." (PMID 41009733, 2025). "Several family members, including WWP1, NEDD4, and ITCH, have been evaluated in the context of obesity using KO mice models." (PMID 41009733, 2025).
Obesity (continued). "Therefore, we conclude that WWP1 may be involved in maintaining WAT function, including the response to oxidative stress, mitochondrial function, and insulin signaling in obesity." (PMID 31965758, 2020).
colorectal cancer (4 papers, 2021 to 2024). A primary or metastatic malignant neoplasm that affects the colon or rectum. "In patients with inflammatory bowel disease (IBD), increased levels of miR-16-5p and miR-21-5p (elevated in ulcerative colitis) suggested WWP1 as a target for these microRNAs, potentially contributing to IBD-associated colorectal cancer (CRC)." (PMID 39949609, 2024). "For example, WWP1 expression at mRNA and protein levels was reported to be commonly increased in colorectal cancer tissues." (PMID 34226507, 2021). "Depletion of WWP1 reduced proliferation and invasion of colorectal cancer cells, while upregulation of WWP1 led to increased proliferative and invasive ability via regulation of the PTEN/Akt pathway." (PMID 34226507, 2021). "In this study, we identified WWP1 as a potential therapeutic target for colorectal cancer." (PMID 39014007, 2024). "Furthermore, miR-16 binds to the 3’UTR of WWP1 and suppresses the growth, proliferation, invasion, and migration of colorectal cancer." (PMID 38129384, 2023). "Similarly, in colorectal cancer, WWP1 overexpression correlates with advanced tumor stages and poor prognosis, with survival analyses indicating significantly reduced survival rates in patients with high WWP1 levels." (PMID 39949609, 2024). "WWP1 could be a potential target of miR-21-5p and miR-16-5p in IBD, and promotes the initiation and progression of IBD-related colorectal cancer." (PMID 34226507, 2021).
oral cancer (4 papers, 2015 to 2023). "It is known that E3 ubiquitin-protein ligase WWP1 is linked to oral cancer." (PMID 34393432, 2021). "We document molecular docking data of E3 ubiquitin-protein ligase WWP1 with compounds ((Stigmasterol, Pyrazinamide, Vasicinone and Ethambutol)) from a medicinal plant Justicia adhatoda L for further consideration in the context of oral cancer." (PMID 34393432, 2021). "Similarly to what was observed in other tumor contexts, WWP1 likely acts as an oncogene also in SCCs and elevated levels of WWP1 has been reported in HNSCC tissues and in several oral cancer cell lines." (PMID 32560247, 2020).
triple-negative breast carcinoma (4 papers, 2021 to 2024). An invasive breast carcinoma which is negative for expression of estrogen receptor (ER), progesterone receptor (PR), and human epidermal growth factor receptor 2 (HER2). "The chemosensitivity of triple negative breast cancer (TNBC) cells is regulated by the circWAC/miR-142/WWP1 ceRNA network via the PI3K/AKT pathway." (PMID 38191906, 2024). "Similarly, circWAC was highly expressed in triple-negative breast cancer, affecting the chemosensitivity of cells through the circWAC/miR-142/WWP1 network." (PMID 35302432, 2022).
heart failure (3 papers, 2022 to 2026). Inability of the heart to pump blood at an adequate rate to meet tissue metabolic requirements. "As an E3 ubiquitin ligase, WW-domain containing protein 1 (WWP1) expression and activity are tightly regulated in cells, while its deregulation has been described in cancer, in neurodegenerative diseases, and in heart failure." (PMID 41891541, 2026).
intrahepatic cholangiocarcinoma (3 papers, 2022 to 2024). A carcinoma that arises from the intrahepatic bile duct epithelium in any site of the intrahepatic biliary tree. "Further studies showed that WWP1 is highly expressed in intrahepatic cholangiocarcinoma (ICC), with elevated levels correlating with poor prognosis." (PMID 39949609, 2024). "However, WWP1-mediated ubiquitination reduces NDFIP1 levels, promoting intrahepatic cholangiocarcinoma (ICC) cell proliferation and migration." (PMID 39949609, 2024).
leukemia (3 papers, 2023 to 2025). A malignant (clonal) hematologic disorder, involving hematopoietic stem cells and characterized by the presence of primitive or atypical myeloid or lymphoid cells in the bone marrow and the blood. "In parallel, TXNIP stabilization upon WWP1 depletion hampers glucose up‐take and glucose metabolism of leukemia cells, with subsequent reduction of ATP production." (PMID 39364720, 2025). "WWP1 inhibits autophagy signal transduction and increases the survival rate of leukemia cells." (PMID 39949609, 2024). "Notably, autophagy activation upon WWP1 depletion inhibited the growth and proliferation of AML blasts and delayed leukemia progression in mice bearing AML cancer, while the ectopic expression of WWP1 accelerated the growth of AML cells." (PMID 36918822, 2023). "The WWP1 downregulation was found to induce autophagy activation which, in turn, suppresses the growth and proliferation of AML blasts and delays leukemia progression in mice bearing AML cancer, showing that WWP1 inhibition can be a valuable therapeutic approach for AML cancer." (PMID 36918822, 2023).
liver cancer (3 papers, 2022 to 2024). An epithelial or non-epithelial malignant neoplasm that arises from the liver. "WWP1 has been implicated as an oncogene in breast, prostate and liver cancer 53-55, and has been identified as a physical PTEN interactor, inducing polyubiquitination of PTEN to suppress its dimerization and membrane recruitment and unleash its tumor suppressive activity." (PMID 36168627, 2022). "However, WWP1 ubiquitinates and degrades KLF14, which lacks a PY motif, suppressing VEPH1 expression and promoting liver cancer cell proliferation, invasion, and migration." (PMID 39949609, 2024).
muscular dystrophy (3 papers, 2020 to 2025). Muscular dystrophy (MD) refers to a group of more than 30 genetic diseases characterized by progressive weakness and degeneration of the skeletal muscles that control movement. "It was reported that WWP1, which is a primary causative protein of chicken muscular dystrophy, also requires its site in β-dystroglycan." (PMID 32825241, 2020). "The primary cause of chicken muscular dystrophy is due to an aberrant WWP1 protein which targets β-dystroglycan as substrate." (PMID 32825241, 2020). "Indeed, a missense mutation in the gene coding WWP1 was identified as the most promising candidate responsible for chicken muscular dystrophy (MD), potentially affecting the E3 function of WWP1 protein." (PMID 33466753, 2021). "WWP1 is a HECT E3 ligase that is involved in chicken muscular dystrophy." (PMID 33466753, 2021).
osteoporosis (3 papers, 2018 to 2024). A condition of reduced bone mass, with decreased cortical thickness and a decrease in the number and size of the trabeculae of cancellous bone (but normal chemical composition), resulting in increased fracture incidence. "C3A, a DNA aptamer, can bind to WWP1 to inhibit its ubiquitination ability, thereby increasing bone deposition for osteoporosis therapy." (PMID 38129384, 2023). "WWP1 plays a vital role in osteoporosis through ubiquitination and degradation of RUNX2 and JUNB and is a potential target of miR-142-5p during bone fracture healing." (PMID 38129384, 2023). "WWP1 and Schnurri-3 (Shn3) proteins are negative regulators of OBs function, and inhibition of WWP1 may promote bone deposition in the treatment of osteoporosis." (PMID 39211390, 2024). "WWP1 and Shn3 proteins negatively regulate Runx2 at the protein level, hence are promising targets to stimulate osteoblast differentiation, and by extension, higher bone mass in osteoporosis patients." (PMID 29518962, 2018). "Since WWP1 and an adapter known as Schnurri-3 are negative regulators of osteoblast function, the disruption of this complex has the potential to increase bone deposition for osteoporosis therapy." (PMID 29518962, 2018). "WWP1 inhibits the differentiation of mesenchymal stem cells (MSCs) into osteoblasts through ubiquitination and proteasomal degradation of JUNB and the lysosomal degradation of CXCR4 following induction by tumor necrosis factor (TNF), thereby promoting inflammation-mediated osteoporosis." (PMID 38129384, 2023).
Troyer syndrome (3 papers, 2018 to 2025). "Hence, loss of WWP1-mediated regulation could result in the development of Troyer syndrome." (PMID 38129384, 2023). "The other two are AIP4/Itch and AIP5/WWP1, confirmed to bind with GRP75 and playing roles in the protein turnover of the Troyer syndrome causative protein Spartin61." (PMID 30250167, 2018). "In conclusion, WWP1’s involvement in various neurological disorders, including autism spectrum disorders, Troyer syndrome, Huntington’s disease, and neuropathic pain, highlights its significance and offers promising avenues for developing novel therapeutic strategies." (PMID 38129384, 2023).
bladder cancer (2 papers, 2014 to 2025). "The mRNA level of WWP1, FBW7 and SMURF2, which have been reported to interact with KLF5 and mediate the ubiquitination of KLF5, were not significantly up-regulated by curcumin in 5637 and WH bladder cancer cells." (PMID 25170806, 2014).
colon cancer (2 papers, 2018 to 2025). "Consistent with previous reports on breast, prostate, and colon cancers, PTEN was identified as a target of WWP1 in PDAC cell lines in which the inhibition of proliferation by WWP1 knockdown was largely reversed by PTEN silencing." (PMID 39656237, 2025).
Hepatic steatosis (2 papers, 2023 to 2025). Steatosis is a term used to denote lipid accumulation within hepatocytes. "By contrast, Wwp1 KO mice and Itch−/− mice exhibit a common phenotype of exacerbated hepatic steatosis." (PMID 41009733, 2025).
Huntington disease (2 papers, 2020 to 2023). Huntington disease (HD) is a rare neurodegenerative disorder of the central nervous system characterized by unwanted choreatic movements, behavioral and psychiatric disturbances and dementia. "WWP1 could contribute to the development of Huntington’s disease (HD) by positively regulating mutant huntingtin protein (mHtt) levels, modulating aggregate formation, and inducing cell toxicity through K63-mediated polyubiquitination of mHtt." (PMID 38129384, 2023).
lung carcinoma (2 papers, 2022 to 2023). "The mRNA level of NEDD4L but not MIB1, WWP1, or other ligases was downregulated in patients with lung cancer." (PMID 37240137, 2023).
myocardial infarction (2 papers, 2024 to 2025). Gross necrosis of the myocardium, as a result of interruption of the blood supply to the area, as in coronary thrombosis. "Xialu’s study confirms that the inhibition of KLF15 ubiquitylation can effectively alleviate the apoptosis induced by the increase of WWP1 expression after myocardial infarction." (PMID 40429972, 2025). "Furthermore, WWP1 can catalyze K48-linked polyubiquitination and degradation by targeting KLF15, triggering excessive cardiomyocyte inflammation after myocardial infarction." (PMID 40429972, 2025). "During the early phase of ischemic myocardial infarction (MI), WWP1 expression is upregulated in cardiomyocytes located at the infarct border." (PMID 38674024, 2024). "WWP1 expression is upregulated in cardiomyocytes located at the infarct border during the early phase of ischemic myocardial infarction (MI)." (PMID 38674024, 2024).
Prostate tumor (2 papers, 2021). "Prostate tumor tissues had 31% of copy number gain of WWP1, but not frequent mutations of WWP1." (PMID 34226507, 2021).
adenoma (1 paper, 2024). A neoplasm arising from the epithelium. "Quantitative IHC analysis revealed significantly elevated WWP1 expression in cancer and metastatic specimens than in normal, adenoma, and para-cancer tissues." (PMID 39014007, 2024). "To evaluate the potential biological role of WWP1 in CRC, we conducted IHC staining on tissue microarrays, including specimens from normal, adenoma, para-cancer, cancer, and metastatic tissues obtained during surgery." (PMID 39014007, 2024).
Atrophy (1 paper, 2021). Any weakening or degeneration, especially through lack of use. "Moreover, HW/TL decreased significantly in WT but not in WWP1 KO mice after TS, suggesting that WWP1 knockout protects against simulated microgravity-induced cardiac atrophy and function decline." (PMID 34733849, 2021).
breast tumors (1 paper, 2021). "WWP1 mRNA was overexpressed in 58% of breast tumor cell lines, which was associated with copy number gain of WWP1." (PMID 34226507, 2021). "The expression of WWP1 was remarkably higher in breast tumors compared with normal tissues." (PMID 34226507, 2021).
chronic lymphocytic leukemia (1 paper, 2021). "The high level of WWP1 mRNA expression was also found in chronic lymphocytic leukemia (CLL) patients and was positively correlated to CD38 and ZAP-70 expressions, indicating that WWP1 might be a potential marker for predicting CLL prognosis." (PMID 34226507, 2021).
developmental and epileptic encephalopathy (1 paper, 2026). An epilepsy associated with developmental impairment that may be due to either the underlying etiology or the superimposed epileptic activity, or both. "In addition, we identified a de novo WWP1 variant in a patient with developmental and epileptic encephalopathy." (PMID 41786693, 2026).
ischemia (1 paper, 2023). A hypoperfusion of the BLOOD through an organ or tissue caused by a PATHOLOGIC CONSTRICTION or obstruction of its BLOOD VESSELS, or an absence of BLOOD CIRCULATION. "Additionally, in vitro experiments also demonstrated abundant WWP1 protein expression, accompanied by low anti-apoptotic protein Bcl2 in neonatal rat cardiac myocytes (NRCMs) exposed to simulated ischemia by deprivation of glucose and oxygen." (PMID 36593958, 2023). "In contrast, double inhibition of WWP1 and KLF15 expressions did not significantly improve ischemia-induced cardiac dysfunction." (PMID 36593958, 2023).
ischemic cardiomyopathy (1 paper, 2023). Ischemic cardiomyopathy is a cardiomyopathy in which a weakness in the muscle of the heart due to inadequate oxygen delivery to the myocardium with coronary artery disease being the most common cause. "In summary, our findings demonstrated a novel role of WWP1 in myocardial ischemic injury and uncovered the mechanism underlying cardiomyocyte inflammatory response, and providing a therapeutic approach for the treating ischemic cardiomyopathy." (PMID 36593958, 2023). "Thus far, the role of WWP1 in ischemic cardiomyopathy remains unclear." (PMID 36593958, 2023).
ischemic heart diseases (1 paper, 2023). "However, previous studies involving WWP1 focused on non-ischemic heart diseases, and it remains unknown whether WWP1 could regulate cardiac dysfunction and infarct size after acute myocardial ischemic injury." (PMID 36593958, 2023).
laryngeal carcinoma (1 paper, 2021). Carcinoma that arises from the laryngeal epithelium. "LncRNA SNGH12 (small nucleolar RNA host gene 12) elevated cell proliferation and invasiveness via acting as a sponger of miR-129-5p and subsequent upregulation of WWP1 in laryngeal cancer cells." (PMID 34226507, 2021). "This study suggested that WWP1 was regulated by SNHG12/miR-129-5p axis in laryngeal cancer." (PMID 34226507, 2021). "In addition, WWP1 was negatively controlled by miR-129-5p in laryngeal cancer cells." (PMID 34226507, 2021). "Upregulation of WWP1 promoted proliferation and invasion of AMC-HN-8 laryngeal cancer cells." (PMID 34226507, 2021).
liver cirrhosis (1 paper, 2015). "Chi-square analysis revealed that the expression of WWP1 in HCC tissues was highly correlated with tumor size (P = 0.015), histological grade (P < 0.001), TNM stage (P < 0.001), vascular invasion (P = 0.018) and tumor capsule (P = 0.026) but not with age, sex, HBV, serum AFP or liver cirrhosis." (PMID 26506518, 2015).
myocardial inflammation (1 paper, 2023). "We observed that I3C (20 mg/kg) pre-treatment for a month alleviated myocardial inflammation by inhibiting WWP1 activity, manifested by up-regulated protein level of KLF15 and obviously suppressed inflammatory signaling pathways." (PMID 36593958, 2023).